ABCB1 (ATP binding cassette subfamily B member 1)
Diseases named in the same sentence as ABCB1 in open-access papers (continued):
Sharing a sentence is not in itself a finding about the gene and the disease.
tuberculosis (9 papers, 2011 to 2026). A chronic, recurrent infection caused by the bacterium Mycobacterium tuberculosis. "Inferior efficacy of antibiotics (e.g. rifampicin) in M2 macrophage-dominant tuberculosis granuloma might be related to poor drug uptake into these cells, potentially mediated by altered expression and activity of drug transporters such as P-glycoprotein (P-gp, encoded by ABCB1)." (PMID 41511522, 2026). "ABCB1 is included in a list of 20 differentially expressed genes in whole blood that distinguish patients with active tuberculosis from healthy individuals." (PMID 37834286, 2023). "ABCB1 is responsible for the transport of many antiretroviral and anti tuberculosis drugs including rifampicin and ethambutol." (PMID 22162992, 2011). "Comparisons of CYP2B6, CYP3A5, NAT2, SLCO1B1 and ABCB1 variant alleles and genotype/haplotypes between DILI non-DILI cases among HIV patients with or without tuberculosis." (PMID 22808112, 2012).
type 2 diabetes mellitus (9 papers, 2015 to 2025). A type of diabetes mellitus that is characterized by insulin resistance or desensitization and increased blood glucose levels. "In addition, immune-related pathways such as allograft rejection, mismatch repair, and protein export were significantly enriched in the high ABCB1 subgroup, but pathways such as osteoclast differentiation and type II diabetes mellitus were enriched in the low ABCB1 subgroup." (PMID 37950194, 2023).
coronary artery disease (8 papers, 2012 to 2022). "Six genes (ABCB1, PLAT, ACE, GH1, PECAM1, and RGS9) known to predispose people to coronary artery disease occur in the cn-LOH regions identified." (PMID 28120895, 2017). "A non-randomized prospective study of 168 patients with coronary artery disease investigated the correlation between CYP2C19 and ABCB1 and ischemic events." (PMID 35806936, 2022).
inflammatory bowel disease (8 papers, 2012 to 2026). A spectrum of small and large bowel inflammatory diseases of unknown etiology. "In a previous study from Denmark, ABCB1 was found to be a “risk gene” for the development of inflammatory bowel disease." (PMID 37090740, 2023). "For example, polymorphisms in ABCB1 have been associated with steroid resistance in children with nephrotic syndrome and steroid response in those with inflammatory bowel disease." (PMID 27688786, 2016). "The gene ABCB1 was down-regulated in LSL and codes for a multidrug resistance protein 1 that is linked to inflammatory bowel disease, comprising Crohńs disease in humans." (PMID 23056453, 2012). "The same mechanism may be important in human which is suggested by the identification of ABCB1 as a ‘risk gene’ in inflammatory bowel diseases." (PMID 23977225, 2013). "The escalating consumption of red meat is a potent environmental risk factor for inflammatory bowel disease (IBD), which is characterized by compromised expression of the xenobiotic transporter P-glycoprotein (MDR1/ABCB1)." (PMID 41745122, 2026). "P-glycoprotein encoded by the ABCB1 gene constitutes a molecular barrier in the small and large bowel epithelium, and its different expression may influence susceptibility to inflammatory bowel disease (IBD)." (PMID 34573401, 2021).
malaria (8 papers, 2015 to 2024). Malaria is a serious and sometimes fatal disease caused by a parasite that commonly infects a certain type of mosquito which feeds on humans. "For this purpose, functional variant alleles in CYP450 (CYP2B6, CYP3A4, CYP3A5) and ABCB1 genes involved in the metabolism of anti-malarial drugs were assessed in pregnant malaria patients treated with ALu." (PMID 28673292, 2017). "We studied the association of single nucleotide variations in human ABCB1 that influences its function in subjects with uncomplicated and complicated malaria caused by Plasmodium falciparum (Pf)." (PMID 28422980, 2017). "ABCB1 is one of the well-studied membrane transporter genes that code for the P-glycoprotein (an efflux protein) and whose effect on malaria disease predisposition and susceptibility to drugs remains to be understood." (PMID 28422980, 2017). "Genotype/allele frequency data of SNPs of ABCB1 gene and the results of the test for genetic association with case (uncomplicated, complicated and all malaria) and control, with measures of statistical significance." (PMID 28422980, 2017). "Kruskal-Wallis test was performed to estimate the effect of genotypes of three polymorphisms on DNA methylation status of ABCB1 gene both in all malaria case (n = 40) and control (n = 40) groups." (PMID 28422980, 2017). "Predicted haplotypes of the SNPs of ABCB1 gene, and statistical analysis of the association to complicated, uncomplicated and malaria patients versus controls." (PMID 28422980, 2017). "Towards this, we tested for global and gene specific DNA methylation changes and association of SNPs in ABCB1 gene in individuals with sub-types of Pf induced malaria." (PMID 28422980, 2017). "In order to identify the risk of individual developing malaria and to predict the outcome, we analysed multiple alterations in ABCB1 and related its impact on the disease." (PMID 28422980, 2017). "The role of ABCB1 variants on CQ pharmacokinetics in malaria treatment should be better investigated in future studies." (PMID 28975866, 2017). "The study provides evidence for multiple mechanisms that may regulate the role of host ABCB1 function to mediate aetiology of malaria susceptibility, prognosis and drug response." (PMID 28422980, 2017). "Apart from epigenetic, the substrate specificity, efflux mechanisms, expression and mRNA stability due to single nucleotide polymorphisms (SNPs) in human ABCB1 may also play a role in determining susceptibility to malaria." (PMID 28422980, 2017). "Our study also revealed the correlation between ABCB1 DNA promoter methylation with rs1128503 and rs2032582 polymorphisms in malaria and was related to increased expression of ABCB1 protein levels in complicated malaria group (p < 0.05) when compared to uncomplicated malaria and control groups." (PMID 28422980, 2017). "In our study, we show that the downstream promoter (+245 to +679) of ABCB1 has low levels of DNA methylation in complicated, uncomplicated and combined malaria groups when we compared to controls." (PMID 28422980, 2017). "Densitometric analysis, normalized to β-actin loading controls, indicated nearly a threefold increase in ABCB1 protein expression in individual with complicated malaria." (PMID 28422980, 2017). "The possible influence of genetic variations in CYP2B6, CYP3A5 and ABCB1 on malaria treatment outcome was evaluated using Cox regression analysis." (PMID 28673292, 2017). "Results obtained from One-way ANOVA test of DNA methylation levels of ABCB1 promoter in complicated, uncomplicated, all malaria and control groups." (PMID 28422980, 2017). "This study reports an association study between the ABCB1 c.3435C>T, CYP3A4*1B (g.-392A>G), CYP3A5*3 (g.6986A>G) SNPs and artemether + lumefantrine treatment outcome in 103 uncomplicated malaria patients from Angola." (PMID 28934955, 2017).
malaria (continued). "Global DNA methylation and ABCB1 DNA promoter methylation levels were performed along with transcriptional response and protein expression in subjects with malaria and healthy controls." (PMID 28422980, 2017). "Our western blot analysis of ABCB1 protein in peripheral mononuclear cells showed higher expression in individuals with malaria than the control group, suggesting that it may have an important role to play in the aetiology of the disease." (PMID 28422980, 2017). "For example, the malaria parasite and its by-products drive DNA hypomethylation and increased expression of the ABCB1 gene, and the hypothesis that this multidrug resistance transporter protein is regulated by malaria infection to eliminate hemoglobin degradation products is being investigated." (PMID 30158923, 2018). "We have shown that +245 to +679 promoter region of ABCB1 that covers the downstream promoter region is significantly methylated in control samples as opposed to samples from malaria subjects." (PMID 28422980, 2017). "No significant influence of CYP2B6, CYP3A5 and ABCB1 c.4036A>Genotypes on malaria treatment outcome were observed." (PMID 28673292, 2017).
acute leukemia (7 papers, 2008 to 2025). A clonal (malignant) hematopoietic disorder with an acute onset, affecting the bone marrow and the peripheral blood. "In this research, we identified ABCB1 as the gene with the highest frequency of single-nucleotide variants (SNVs) associated with chemotherapy response in acute leukemias, found in 12.5% of AML and 10.5% of ALL cases." (PMID 41301675, 2025). "Further research is required to elucidate the role of ABCB1 promoter methylation also in other subtypes of acute leukemia." (PMID 33066132, 2020). "Finally, acquired pinometostat resistance led to the upregulation of the multidrug efflux pump ABCB1, associated with multidrug resistance and previously reported as the mechanism of pinometostat resistance in KMT2A-rearranged acute leukemia cell lines." (PMID 37740239, 2023).
B-cell lymphoma (7 papers, 2007 to 2025). "Drug resistance to doxorubicin has been associated with increased p-glycoprotein in canine B-cell leukemia cell lines, and increased ABCB1 expression was associated with acquired (but not intrinsic) drug resistance to doxorubicin in dogs with B cell lymphoma in another study." (PMID 37624862, 2023). "Also in the human B-cell lymphoma cell line, the activation of the MAPK/ERK pathway was shown to upregulate ABCB1 gene expression through increased expression or nuclear translocation and DNA-binding activity of YB-1, the transcription factor that regulates ABCB1 gene expression." (PMID 29061940, 2015).
chronic lymphocytic leukemia (7 papers, 2016 to 2025). "In three tumor samples from patients with chronic lymphocytic leukemia (CLL), ABCB1 promoter methylation levels were inversely correlated with ABCB1 mRNA levels." (PMID 33066132, 2020).
colorectal adenocarcinoma (7 papers, 2012 to 2025). The most common type of colorectal carcinoma. "Its cytotoxicity, ability to change doxorubicin (Dox) accumulation and resistance to this drug, as well as ABCB1 inhibition potency were studied in drug-sensitive and resistant human colorectal adenocarcinoma cells (HT29), and in the variant of MDCK cells expressing human ABCB1 protein." (PMID 34361789, 2021). "Human colorectal adenocarcinoma cells overexpressing the ABCB1 efflux pump showed this effect." (PMID 40362377, 2025). "We also used human HCT-15 (colorectal adenocarcinoma) cells that endogenously express ABCB1." (PMID 39003409, 2024). "ABCB1 −129C showed association with the reduced mRNA expression in both colorectal adenocarcinomas and adjacent noncancerous colorectal tissues in Japanese subjects." (PMID 23050008, 2012). "In addition, a recent report shows that Histone Deacetylase 1 and 2 (HDAC1 and 2) have a reciprocal relationship to RB1 and are able to reduce ABCB1 and ABCC2 gene and protein expression in colorectal adenocarcinoma and carcinoma cell lines." (PMID 26799285, 2016). "A similar observation was previously made for the prenylated flavonoid 8-prenylnaringenin, which was able to reduce Dox accumulation and inhibited ABCB1 activity in Dox-resistant colorectal adenocarcinoma cells (LoVo/Dx), but was not able to affect Dox cytotoxicity." (PMID 34361789, 2021).
dementia (7 papers, 2006 to 2026). Loss of intellectual abilities interfering with an individual's social and occupational functions. "The objective of the study is to investigate the ABCB1 3435C>T (rs1045642) polymorphism with AD susceptibility, dementia severity, and cognitive impairment in an Egyptian cohort." (PMID 41882463, 2026). "The aim of this study was to assess the usefulness of ABCA1, ABCB7, ABCB1, APOE, CYP46A1, and LRP1 genotyping as promising dementia risk factors among a wide group of patients diagnosed first with hyperlipidemia." (PMID 41226793, 2025). "This first study on ABCB1 genotypes in dementia has 27% power to detect differences in C3435T genotypes between AD and control patients." (PMID 16999857, 2006). "We hypothesized ABCB1 genotypes to be related to dementia occurrence as amyloid load in the brain is possibly inversely related to P-gp expression at the BBB and ABCB1 SNPs and haplotypes may be related to P-gp expression and function." (PMID 16999857, 2006). "ABCB1 genotype, allele and haplotype frequencies were neither significantly different between patients with dementia and age-matched controls, nor between subgroups of different types of dementia nor age-matched controls." (PMID 16999857, 2006). "ABCB1 genotypes are presently not useful as a biomarker for dementia, as they were not significantly different between demented patients and age-matched control subjects." (PMID 16999857, 2006).
esophageal cancer (7 papers, 2012 to 2024). A primary or metastatic malignant neoplasm involving the esophagus. "It was also shown in oesophageal cancer that the presence of 7q21.12 amplification, where the ABCB1 gene is located, is associated with the resistance of tumour cells to taxanes." (PMID 35631534, 2022). "Further research investigating the ABCB1 expression in esophageal carcinoma and esophageal mucosa tissue is warranted to elucidate the relationship between response and ABCB1 status." (PMID 34858183, 2021). "The difference in ABCB1 expression between the different types of tissues could also be used to improve treatment with carboplatin and paclitaxel in esophageal cancer." (PMID 34858183, 2021). "Moreover, the expression of ABCB1 by esophageal carcinomas is higher compared to normal-appearing esophageal mucosa." (PMID 34858183, 2021). "Available studies suggest that expression of several ABC proteins (ABCB1, ABCC2, and ABCG2) correlates with prognosis or response to therapy in esophageal cancer patients." (PMID 33390934, 2020). "The mutations in ABCB1 and SEMA5A described here have not been previously reported in oesophageal cancer." (PMID 27600491, 2016).
heart failure (7 papers, 2018 to 2025). Inability of the heart to pump blood at an adequate rate to meet tissue metabolic requirements. "In addition, ABCG2 can prevent cardiac hypertrophy and heart failure caused by pressure overload, and suppression of inherent ABCB1 elevates the susceptibility to doxorubicin-induced cardiotoxicity." (PMID 40755506, 2025).
neuropathy (7 papers, 2014 to 2021). A disorder affecting the nervous system that manifests with pain, tingling, numbness, and/or muscle weakness. "Other studies demonstrated an involvement of ABCB1 gene polymorphisms encoding for P-glycoprotein, a primary protein involved in taxane elimination and distribution, with neuropathy in metastatic breast cancer patients treated with paclitaxel or docetaxel monotherapy." (PMID 28286483, 2017). "Patients treated with docetaxel carrying another ABCB1 2677GG genotype had a significantly longer time to neuropathy." (PMID 28286483, 2017). "On the other hand, CYP2C8, ABCB1, EPHA5, EPHA6 and TUBB2A were found to be associated with taxane-induced neuropathy in more than one study, but not to be associated with platinum-induced neuropathy." (PMID 26269716, 2015). "At our hospital, we also observed severe neuropathy in CYP3A5 poor metabolizers independent of CEP72 and ABCB1 status." (PMID 27618021, 2016).
rhabdomyosarcoma (7 papers, 1995 to 2023). A rare aggressive malignant mesenchymal neoplasm arising from skeletal muscle. "Among them, P-glycoprotein (P-gp/MDR1/ABCB1) is associated with resistance to commonly used chemotherapeutic agents in rhabdomyosarcoma." (PMID 37958442, 2023). "Finally, downregulation of ABCB1 by a preincubation with simvastatin was sufficient to result in reduced calcein efflux rates in rhabdomyosarcoma (RD) cells." (PMID 26319048, 2016). "One of the articles reported no results using the cellular line of rhabdomyosarcoma, and the other found overexpression of ALDHA3, ALDHB1, ALDHL2, SOX2, ABCG2, ABCB1, and ABCA2 markers." (PMID 37173919, 2023).
breast adenocarcinoma (6 papers, 2016 to 2023). "ER stress could be induced by treating ABCB1-overexpressing MCF-7/KCR MDR breast adenocarcinoma cells with silver nanoparticles of 75 nm diameter or with different dihydrotestosterone derivatives." (PMID 36839907, 2023). "For this purpose, we used a DOX-resistant subline of the human breast adenocarcinoma cell line MCF-7, KCR, which is characterized by overexpressing ABCB1." (PMID 32340269, 2020).
Crohn disease (6 papers, 2012 to 2025). A gastrointestinal disorder characterized by chronic inflammation involving all layers of the intestinal wall, noncaseating granulomas affecting the intestinal wall and regional lymph nodes, and transmural fibrosis. "Knockout or low-activity alleles of ABCB1 lead to dysbiosis, Crohn's disease and ulcerative colitis in mammals." (PMID 38497255, 2024). "Indeed, low-activity variants of ABCB1 in the human population have now been linked to a higher susceptibility to Crohn's disease (CD) and ulcerative colitis (UC)." (PMID 38497255, 2024). "For example, our results may be relevant to a report linking the ABCB1 G3435T polymorphism to efficacy of corticoid therapy in patients with Crohn’s disease." (PMID 29083397, 2015).
Hepatic steatosis (6 papers, 2011 to 2025). Steatosis is a term used to denote lipid accumulation within hepatocytes. "In this study, through network pharmacology and molecular docking, we identified potential targets for Catechin gallate in the treatment of fatty liver disease, which include ABCB1, DYRK1A, PGD, and FUT4." (PMID 40699724, 2025). "We found out for the first time that hepatic mRNA of both Abcb1a/Mdr1a and Abcb1b/Mdr1b genes, as well as protein content of ABCB1, was significantly decreased in fenofibrate-treated hypertriglyceridemic rats with moderate hepatic steatosis." (PMID 30787874, 2019). "In conclusion, our preliminary result demonstrated that fenofibrate treatment and especially the overdose of rats with chronic hypertriglyceridemia and mild hepatic steatosis decreased mRNA of Abcb1a/Mdr1a and Abcb1b/Mdr1b genes as well as the protein content of ABCB1." (PMID 30787874, 2019). "Furthermore, based on network pharmacology predictions, molecular docking studies suggested that the primary targets of Catechin gallate in alleviating fatty liver might include ABCB1, DYRK1A, PGD, and FUT4." (PMID 40699724, 2025).
Hyperglycemia (6 papers, 2015 to 2022). An increased concentration of glucose in the blood. "The permeability-glycoprotein; ABCB1 low protein levels in STZ-rats are in concert with a previous report, in which hyperglycemia inhibited Pgp expression, thus explaining the provoked STZ toxicity on both pancreatic and renal cells, due to inefficient foreign-substances pumping out of cells." (PMID 34698133, 2021).
leukopenia (6 papers, 2011 to 2025). "Polymorphic variants in the efflux transporter gene ABCB1 may predict fluorouracil, adriamycin, and cytoxan (FAC) regimen’s myelotoxicity, except for leukopenia." (PMID 40283974, 2025). "In this study polymorphic variants in genes encoding membrane transporters, both influx (SLC22A16) and efflux ones (ABCB1, ABCG2, ABCC2), were the independent predictors of all studied symptoms of FAC myelotoxicity, excluding overall leukopenia." (PMID 29507678, 2018).
nasopharyngeal carcinoma (6 papers, 2015 to 2024). A carcinoma arising from the nasopharyngeal epithelium. "Interestingly, for Asian nasopharyngeal carcinoma patients, polymorphisms in the ABCG2 and ABCB1 genes could be predictive markers of drug (irinotecan) activity." (PMID 25965825, 2015). "USP9X upregulates the expression of ABCB1 and MRP2 by stabilizing β-catenin, thus affecting cisplatin resistance in nasopharyngeal carcinoma (NPC) cells." (PMID 36694209, 2023).